EVPL (envoplakin)
Description:
Component of the cornified envelope of keratinocytes. May link the cornified envelope to desmosomes and intermediate filaments.
Synonyms: EVPK
Tractability: Antibody: its Gene Ontology location is reachable by antibodies, with high confidence. PROTAC: ubiquitination databases record sites on it.
Gene: Protein-coding gene on chromosome 17 (76,004,502 to 76,027,438, reverse strand). Ensembl gene ENSG00000167880.
Subcellular location: Cell junction, desmosome; Cornified envelope; Cytoplasm, cytoskeleton
Subcellular location (Human Protein Atlas): Intermediate filaments; Cytosol
Pathways (Reactome):
Developmental Biology: Formation of the cornified envelope
Gene Ontology:
Molecular function: cadherin binding; structural molecule activity
Biological process: keratinocyte differentiation; peptide cross-linking; epidermis development; intermediate filament cytoskeleton organization; wound healing
Cellular component: cornified envelope; cytosol; extracellular exosome; intermediate filament cytoskeleton; cytoplasm; intermediate filament; membrane; cytoskeleton; desmosome
Genetic constraint (gnomAD): Loss-of-function variants: 101 observed, 119.29 expected, observed/expected ratio (o/e) 0.85, 90% interval 0.72 to 1. The upper end of that interval is the gene's LOEUF score, 1, which puts it in group 4 of 6, group 1 being the genes least tolerant of losing a copy. Missense variants: 2,612 observed, 2,647.4 expected, observed/expected ratio (o/e) 0.99, 90% interval 0.95 to 1.02. Synonymous variants: 1,169 observed, 1,139.8 expected, observed/expected ratio (o/e) 1.03, 90% interval 0.98 to 1.08.
Homologues: Orthologues: chimpanzee EVPL (99% identical), macaque EVPL (96% identical), dog EVPL (85% identical), mouse Evpl (83% identical), guinea pig EVPL (81% identical), rat Evpl (80% identical), pig EVPL (75% identical), rabbit EVPL (75% identical), tropical clawed frog evpl (54% identical), zebrafish evpla (43% identical). Paralogues in human: PPL (26% identical), EVPLL (11% identical).
Diseases named in the same sentence as EVPL in open-access papers:
EVPL is named in the same sentence as 56 diseases in open-access papers, as found by Europe PMC text mining. Sharing a sentence is not in itself a finding about the gene and the disease. The quoted sentences say what the papers report.
melanoma (7 papers, 2011 to 2025). A malignant, usually aggressive tumor composed of atypical, neoplastic melanocytes. "For melanoma progression category (T3, T4 and MM), only genes ontologically-related to hKLKs (EVPL, KLK6, KLK7, KLK8, KLK13 and SERPINB13) showed a positive and high correlation coefficient (mean of 0.971) in T4 thick melanomas (depth > 4.0 mm), but not in metastatic tumors (MM)." (PMID 22032772, 2011). "The enrichment of these categories reflects the dysregulation of transcriptional programs typical of keratinocytes (e.g., SPRR1/2/3, KRT10/KRT16, LOR, IVL, EVPL, SCEL, TGM1/TGM3, CERS3, ACER1, DSP) and, above all, the epithelial crosstalk that influences melanoma biology." (PMID 41465101, 2025).
paraneoplastic pemphigus (5 papers, 2018 to 2022). Pemphigus is a group of chronic autoimmune skin diseases characterized by blisters formation on the outer layer of the skin and the mucous membranes. "Autoimmunity to envoplakin is associated with paraneoplastic pemphigus (also known as paraneoplastic autoimmune multiorgan syndrome)." (PMID 35870560, 2022). "Due to their high specificity (91–100%), anti-envoplakin autoantibodies are considered an important diagnostic marker for paraneoplastic pemphigus." (PMID 31552014, 2019). "However, paraneoplastic pemphigus serum autoantibodies typically cause an intercellular binding pattern in the epidermis and can bind to rat bladder epithelia and to envoplakin and periplakin." (PMID 31312198, 2019). "It has been reported that the level of envoplakin was elevated in the serum of paraneoplastic pemphigus patients before oral prednisolone treatment and decreased with a decline in disease activity after treatment." (PMID 35252347, 2022). "Envoplakin is also a component of the antigen complex in paraneoplastic pemphigus (an autoimmune blister skin disease)." (PMID 35252347, 2022). "Commercial ELISA systems (MBL, Euroimmun) are available for the detection of autoantibodies against Dsg1 and Dsg3 in pemphigus and against envoplakin in paraneoplastic pemphigus." (PMID 31552014, 2019). "A cumulative autoimmune response to periplakin, envoplakin, BPAG1, and desmoplakin has been described in persons affected by paraneoplastic pemphigus that results in a dismal prognosis with a 75–90% mortality rate and a mean survival < 1 year." (PMID 29373494, 2018).
diabetes (3 papers, 2015 to 2025). "Uromodulin (UMOD) demonstrated the most significant change, increasing by 3.19-fold in the case of diabetes, while envoplakin (EVPL) showed the most substantial decrease in the case of diabetes." (PMID 40142159, 2025).
autosomal dominant polycystic kidney disease (2 papers, 2020 to 2023). Autosomal dominant form of polycystic kidney disease. "This suggests that envoplakin, periplakin, and villin-1 may be used as biomarkers to differentiate between autosomal dominant polycystic kidney disease (ADPKD) patients with or without CKD." (PMID 37510273, 2023).
ovarian carcinoma (2 papers, 2021 to 2024). A malignant neoplasm originating from the surface ovarian epithelium. "We have recently shown the expression of PLEC, PPL, and EVPL in benign and malignant ovarian tumours." (PMID 39682273, 2024). "In this review article, we explore the roles of plakins, particularly plectin, periplakin and envoplakin in disease-states and cancers with emphasis on ovarian cancer." (PMID 34001250, 2021).
skin cancer (2 papers, 2018 to 2024). "In contrast, another mouse model deficient in envoplakin, periplakin, and involucrin (Epi−/− mice), three components of the epidermal barrier on which the cornified envelope assembles, have a defective epidermal barrier that is protective against skin cancer." (PMID 39625985, 2024).
autoimmune disease (1 paper, 2023). A disorder resulting from loss of function or tissue destruction of an organ or multiple organs, arising from humoral or cellular immune responses of the individual to their own tissue constituents. "NOSTRIN connects to another nitric oxide gene, NOS3, RNF115 to the RAS oncogene family member RAB7A, while SPRR2A connects with EVPL (associated with squamous cell cancer and autoimmune disease)." (PMID 38030619, 2023).
follicular thyroid cancer (1 paper, 2021). "Envoplakin (EVPL) is a protein component of desmosomes and the DNA variant in intron of EVPL (rs2071194) has been found associated with papillary and follicular thyroid cancer risk." (PMID 33842346, 2021).
Hyperkeratosis (1 paper, 2016). Hyperkeratosis is a histopathological term defining a thickened stratum corneum and may be present in many different skin conditions, with many possible overlaps. "Moreover, mice deficient in INVOLUCRIN, ENVOPLAKIN, and PERIPLAKIN show barrier defects, decreased desquamation, and hyperkeratosis that is concomitant with decreased KLK activity." (PMID 27551807, 2016).
keloid (1 paper, 2022). An irregularly shaped, elevated mark on the skin caused by deposits of excessive amounts of collagen during wound healing. "Moreover, several proteins that play a role in cell junctions were also downregulated in keloids, including EVPL, PPL, DSP, PKP1, PKP3, DSC1, DSG1, and FLG." (PMID 35435317, 2022). "Most keratins and cell junction related proteins such as KRT10, EVPL, PPL, and DSP were downregulated in keloids." (PMID 35435317, 2022).
papilloma (1 paper, 2014). A benign epithelial neoplasm that projects above the surrounding epithelial surface and consists of villous or arborescent outgrowths of fibrovascular stroma. "We observed a downregulation of envoplakin, periplakin, and involucrin in WT papillomas and SCCs, leading us to speculate that the increased risk of SCC conversion in EPI−/− papillomas may be linked to the lack of two desmosomal proteins." (PMID 24843010, 2014).
pemphigus (1 paper, 2024). Pemphigus is a group of rare autoimmune diseases that cause blistering of the skin and mucous membranes (mouth, nose, throat, eyes, and genitals).This conditioncan occur at any age, but often strikes people in middle or older age. "Furthermore, the rat bladder is rich in plakins such as envoplakin and periplakin, making it highly specific for differentiating PNP from other forms of pemphigus." (PMID 39584995, 2024).
psoriasis (1 paper, 2025). An autoimmune condition characterized by red, well-delineated plaques with silvery scales that are usually on the extensor surfaces and scalp. "However, unlike EPPK1, EVPL and PPL were not downregulated in lesional psoriasis, indicating a unique role of EPPK1 in psoriatic pathogenesis." (PMID 40746860, 2025).
cancer (7 papers, 2016 to 2024). A tumor composed of atypical neoplastic, often pleomorphic cells that invade other tissues. "Sequencing of somatic cancers has identified 18 mutations in envoplakin's PRD including Y1831F, D1832Y, D1981N and R1999C27." (PMID 26935805, 2016). "More recently, envoplakin and periplakin, functioning as epidermal barrier components, have also attracted attention in cancer development." (PMID 29587367, 2018). "In cancer, reduced expression of PPL and EVPL have been observed in oesophageal cancers, and the cellular localisation of PPL was noted to change with disease progression." (PMID 34001250, 2021). "Downexpressions of EVPL and PPL can also be found in the majority of datasets (26 for EVPL and 51 for PPL) across the cancer types." (PMID 29587367, 2018).
tumor (7 papers, 2011 to 2025). "In this study we demonstrate that the expression of PPL and EVPL is lower in the benign samples than in the Type I tumours." (PMID 39682273, 2024). "Previously we have shown that plakins (PPL, DSP, PLEC, EVPL) expressed in the ascites-derived tumour cells from patients with chemotherapy-treatment associated recurrence were significantly lower than plakins (PPL, DSP, EVPL, PLEC) in chemonaive ascites-derived tumour cells." (PMID 34001250, 2021). "Other proteins of specific interest down regulated in CR tumor cells were members of plakin family such as PPL, EVPL and Plectin which function as ‘molecular bridges’ linking the intracellular cytoskeleton and cell-cell junctions." (PMID 27470985, 2016). "To test whether this influences tumour formation, we chemically induced tumours in EPI−/− mice, which lack three barrier proteins—Envoplakin, Periplakin, and Involucrin." (PMID 24843010, 2014).
benign tumours (1 paper, 2014). "Thus combined deletion of envoplakin, periplakin, and involucrin decreased epidermal susceptibility to chemically induced benign tumours." (PMID 24843010, 2014).
EVPL also shares sentences with these, for which no sentence is quoted: chronic myeloid leukemia (28 papers); leukemia (17); atherosclerosis (10); acute lymphoblastic leukemia (9); metastatic melanoma (3); myeloproliferative neoplasm (3); acute myeloid leukemia (2); aortic atherosclerosis (2); cardiovascular disease (2); COVID-19 (2); cutaneous melanoma (2); infection (2); myeloid leukemia (2); acute leukemia (1); aortic aneurysm (1); Autoimmunity (1); breast carcinoma (1); chronic myelomonocytic leukemia (1); chronic neutrophilic leukemia (1); coronary atherosclerosis (1); eczema (1); essential thrombocytemia (1); follicular lymphoma (1); gout (1); Hypercholesterolemia (1); Hypertension (1); infarction (1); lymphoid leukemia (1); lymphoid tumors (1); lymphoma (1).
A further 10 diseases each share a sentence with EVPL in 1 paper.